TLR9 (toll like receptor 9)
Diseases named in the same sentence as TLR9 in open-access papers (continued):
Sharing a sentence is not in itself a finding about the gene and the disease.
melanoma (continued). "In the INTRIM trial, patients with stage II pT3-4/cN0 melanoma had significantly reduced tumour positive sentinel lymph node rates after presurgical single-dose treatment with the toll-like receptor-9 (TLR9) agonist IMO-2125 compared with placebo." (PMID 37507765, 2023). "SD-101 is a TLR-9 agonist that has been studied in combination with pembrolizumab in patients with advanced melanoma without prior exposure to anti-PD-1 therapy under a phase IB/II study (SYNERGY-001/KEYNOTE-184)." (PMID 36831449, 2023). "Additionally, lefitolimod and cavrotolimod are TLR9 agonists being evaluated in solid tumors, while tilsotolimod and vidutolimod/CMP-001 are TLR9 agonists being tested in melanomas." (PMID 37686661, 2023). "Importantly, CMP-001 can directly trigger TLR9 on NK cells, improving the anti-PD1 mAb treatment in melanoma mouse models." (PMID 36672572, 2022). "Moreover, another study showed that activation of Toll-like receptor-9 (TLR-9) by CpG (TLR-9 ligand) enhanced the maturation and differentiation of MDSCs, and effectively decreased the percentage of Ly6Ghi MDSCs in melanoma and CRC tumor models." (PMID 36081407, 2022). "TLR-9 agonists augment function of antigen-specific CD8+ T cells and, in melanoma, have shown evidence of immunogenicity in combination with cancer vaccines and promising activity as a single-agent or in combination with anti-PD-1 blockade in PD-1 naïve and PD-1-refractory patients." (PMID 35449104, 2022). "The three major receptors responsible for DNA-driven immune responses include toll-like receptor 9 (TLR9), absent in melanoma 2 (AIM2) and cyclic-GMP-AMP synthase (cGAS)." (PMID 35961978, 2022). "Recombinant MAGE-A3 vaccination with the AS15 immunostimulant, which contains CpG, a TLR9 stimulant, was assessed in patients with melanoma and non-small cell lung cancer but did not produce a survival benefit." (PMID 31980914, 2020). "Compared with B16-Ova, the non-immunogenic B16-F10 melanoma was significantly less responsive to monotherapy treatments; however, TLR9 agonist (p = 0.0054), anti-CTLA-4 (p = 0.0125) and anti-PD-1 (p = 0.0283) all showed a modest capacity to extend survival." (PMID 31771649, 2019). "Finally, we show that by combining both an enhanced potency TLR9 agonist (MGN1703) and a depletion-optimized CTLA-4 antibody (9D9-mIgG2a), half of pre-implanted parental B16-F10 melanoma can be cured." (PMID 31771649, 2019). "Next, in the non-immunogenic B16-F10 melanoma model, we showed that only intra-tumoral, but not systemic TLR9 activation augments the therapeutic potential of checkpoint blockade." (PMID 31771649, 2019). "Given the lack of potentiation of local TLR9 agonist activity by local checkpoint blockade against this poorly immunogenic melanoma, we explored the potential of systemic administration of these immunotherapies." (PMID 31771649, 2019). "The presence of plasmocytoid dendric cells (pDCs) expressing TLR7 and TLR9 receptors in the inflammatory infiltrate of melanoma metastasis is crucial for treatment with two potent immune stimulators after ECT, such as imiquinod, a TLR7 agonist, and GpG-ODN, a TLR9 agonist." (PMID 26155423, 2015). "Using a mouse model of melanoma metastasis induced by intravenous injection of B16-F10 cells, we investigated the mechanism responsible for the diverse efficacy of the prophylactic or therapeutic TLR4 and TLR9 agonist complex against metastasis." (PMID 21931823, 2011). "100% of B16 melanoma cells were stained with anti-TLR9 antibodies, regardless of PI staining." (PMID 38791341, 2024). "The recognition of cfDNA could be performed by the DNA-sensing receptor cyclic guanosine monophosphate (GMP)-adenosine monophosphate (AMP) synthase (cGAS), Toll-like receptor 9 (TLR9), or absent in melanoma-2 (AIM2)-like receptors (ALRs)." (PMID 36359370, 2022).
melanoma (continued). "Finally, we did not observe TLR3, TLR7 or TLR9 expression in previously published RNA-Seq data of in vitro cultured B16F10 melanoma (data not shown), ruling our direct effects of agonist treatment on the tumor itself." (PMID 34381732, 2021). "Indeed, there are several preclinical and clinical studies of ISV utilizing TLR9 agonists, IMO-2125 (B type), SD-101 (C type), MGN1703 (C type) and CMP-001 (D type), in combination with pembrolizumab, atezolizumab, or ipilimumab for melanoma, lung cancer, pancreatic cancer and colorectal cancer." (PMID 35136110, 2022). "In mammals, DNA recognition is carried out by Toll-like receptor (TLR9), cyclic GMP–AMP synthase, and “absent in melanoma 2” (AIM2), depending on its localization in either the endosomal compartment or the cytoplasm." (PMID 40407422, 2025). "Several DNA sensors capable of recognizing cfDNA have been identified, including Toll-like receptor 9 (TLR9) within endosomes and cytoplasmic sensors like cyclic GMP-AMP synthase (cGAS) and absent in melanoma 2 (AIM2)." (PMID 39687793, 2024).
Autoimmunity (83 papers, 2008 to 2026). The occurrence of an immune reaction against the organism's own cells or tissues. "The two analyzed polymorphisms in the TLR9 gene promoter region have been linked to autoimmunity and gene transcription rate." (PMID 31781672, 2019). "Furthermore, certain haplotypes within the TLR9 gene have the potential to impact the activation of its defense mechanism, thereby influencing the susceptibility or resistance to autoimmune disorders." (PMID 40821978, 2025). "Indeed, in contrast to TLR4, the dysregulation of TLR9 signaling has been associated with autoimmunity, even though its precise role is still a subject of debate." (PMID 30900780, 2019). "Interestingly, TLR9-deficient mice are known to develop general autoimmunity due to spontaneous B-cell activation." (PMID 29101363, 2017). "Accordingly, activation of TLR9 by endogenous ligands has been reported to be protective in autoimmunity, and TLR9-deficient mice exhibit exacerbated symptoms of myelin oligodendrocyte glycoprotein- (MOG-) induced EAE, as well as an enhanced susceptibility to experimental type 1 diabetes." (PMID 28356656, 2017). "TLR9 may also interact with host nuclear DNA as well as mitochondrial DNA released from dying cells during infections and inflammation, which contributes to an increased risk for autoimmunity." (PMID 37834438, 2023). "Cytosolic mitochondrial DNA can then activate proinflammatory signaling pathways, mediated by TLR9 and cGAS, as well as inflammasomes, triggering inflammation and autoimmunity." (PMID 41011480, 2025). "Uncontrolled TLR7, TLR8, or TLR9 activation can lead to responses to self-nucleic acids and autoimmunity." (PMID 38780621, 2024). "Our results reveal a posttranslational modification cycle that controls TLR9 response and autoimmunity." (PMID 38169466, 2024). "In conclusion, NETs-DNA promotes NF-κB-dependent autoimmunity via cGAS/TLR9 in long-term CS exposure-induced COPD." (PMID 38880789, 2024). "In the context of autoimmunity, since TLR9 is involved in self-DNA recognition, it is likely that autoreactive FO B cells are stimulated by TLR9 and induce PC differentiation in an elevated IFNα environment." (PMID 38659975, 2024). "Studies show that overactivation or impaired function of the TLRs that detect nucleic acids, TLR7 and TLR9, induces dysfunction of innate immunity and breakdown of immune tolerance, which can lead to the occurrence of autoimmunity." (PMID 36875095, 2023). "This confirms TLR9 mediated dendritic cell activation as a mechanism of anti-MPO autoimmunity in AAV and further defines the link between infection and the generation of MPO specific autoimmune inflammation." (PMID 36674855, 2023). "In fact, TLR9 has a complex dual regulatory mechanism in B cells, which can both maintain immune tolerance and participate in autoimmunity." (PMID 36875095, 2023). "The enhanced MPO autoimmunity induced by TLR9 stimulated dendritic cells facilitates leukocyte recruitment into the glomerulus and histological and functional kidney injury akin to that seen in MPO-AAV." (PMID 36674855, 2023). "Our results point to an important role for BCR/TLR9 crosstalk in the perpetuation of autoimmunity by counteracting unresponsiveness of each of these receptors that occurs when activated autoreactive B cells evolve into functionally exhausted CD21low B cells." (PMID 36845129, 2023). "Our study reflects the importance of both Th1 and Th17 responses in the pathogenesis of TLR9 mediated anti-MPO autoimmunity and consequent kidney injury." (PMID 36674855, 2023). "TLR9 has been demonstrated to be an important mediator of autoimmunity and glomerular inflammation in a murine model of MPO-AAV." (PMID 36674855, 2023). "In summary this study demonstrates that MPO pulsed dendritic cells activated ex vivo through TLR9 ligation promote anti-MPO autoimmunity when transferred to naïve mice." (PMID 36674855, 2023).
Autoimmunity (continued). "TLR9 stimulated MPO pulsed dendritic cells promote anti-MPO autoimmunity by driving Th1 and predominantly Th17 immune responses." (PMID 36674855, 2023). "TLR9 ligation has been shown to promote anti-MPO autoimmunity and glomerular vasculitis in murine MPO-AAV." (PMID 36674855, 2023). "In AAV, major toll-like receptor 2 (TLR2) and toll-like receptor 9 (TLR9) activation can provoke autoimmunity." (PMID 35632497, 2022). "AIM-100, an inhibitor of ACK1, can significantly inhibit TLR4/TLR7/TLR9-induced activation of macrophages and DCs and alleviates the TLRs-mediated inflammation and autoimmunity." (PMID 35669783, 2022). "We will briefly introduce nucleic acid TLRs and present data for the interplay of TLR7 with TLR8 and TLR9 and its importance in autoimmunity." (PMID 36389822, 2022). "The functional interaction between TLR7 and TLR9 within B cells is important for B-cell dysregulation in autoimmunity." (PMID 36220996, 2022). "Pharmaceutical inhibition of PKM2 by PKM2-IN can inhibit TLR4/TLR7/TLR9-induced activations of macrophages, DCs and B cells, and alleviate the pathogenesis of TLRs-mediated inflammation and autoimmunity." (PMID 34025679, 2021). "In this work, the authors elucidated a role for Gal9 in restraining TLR7 and TLR9 responses in pDCs, important drivers of type I IFNs and the inflammatory profile that supports autoimmunity." (PMID 34369876, 2021). "When excessive cellular or tissue damage occurs, the activation of TLR7 or TLR9 by endogenous nucleic acids can be exacerbated, leading to autoimmunity phenomena." (PMID 34458163, 2021). "Although TLR7 and TLR9 are similar in structure and involved in autoimmunity by recognizing self-RNA and self-DNA, respectively, contradictory actions for autoimmune disease models are observed." (PMID 33371432, 2020). "In the host body, particular caution is required in activating nucleic-acid-sensing TLRs, such as TLR3, TLR7, and TLR9, to avoid self-recognition and thus the induction of autoimmunity." (PMID 31892731, 2019). "In this review, we have discussed up‐to‐date knowledge of the regulation of the pathways elicited by TLR4 and TLR9 and their roles in host defense and autoimmunity." (PMID 30900780, 2019). "This scenario, if confirmed in vivo, would enlarge the current perspective on the role of TLR9 in autoimmunity." (PMID 30546358, 2018). "In line, Tlr9-deficient C57BL/6 mice display less autoimmunity and nephritis due to less glomerular Ig-deposits and complement activation in pristane-induced autoimmunity." (PMID 29650017, 2018). "TLR7/TLR9 responses have substantiated roles in both autoantibody production and autoimmunity, especially in B cell receptor (BCR)-activated B cells." (PMID 28751890, 2017). "Since immune dysregulation and autoimmunity was largely confined to the B cell compartment, results suggest that the TLR9 and TLR7 effects were B-cell intrinsic." (PMID 28751890, 2017). "In fact, the implication of TLR9 activation in mouse models has complex consequences as TLR9 on B cells restrains TLR7-mediated spontaneous autoimmunity in C57BL/6 mice." (PMID 28970832, 2017). "Immunotherapeutic applications of CpG-ODN as TLR9 agonists include not only approaches to enhance immune responses, but also immunosuppressive strategies, as is the case for treating allergy and autoimmunity." (PMID 28356656, 2017). "Paradoxically, TLR9 also plays known protective roles against autoimmunity by directly and indirectly inhibiting TLR7-mediated autoantibody production." (PMID 28751890, 2017). "Opposing effects were described for TLR7 and TLR9: deletion of TLR7 limited autoimmunity, whereas TLR9 deletion paradoxically exacerbated disease." (PMID 26137972, 2015). "Since costimulation of B cells via BCR and TLR9 was shown to break tolerance and induce autoimmunity, we were interested to study the effect of dual BCR and TLR9 signals on MAPK activation in B cells of RA patients." (PMID 24801688, 2014).
Autoimmunity (continued). "Wan and colleagues demonstrated that IRAK-2 suppresses TLR9 signaling in the early post-stimulation phase, raising the activation threshold for TLR9-induced inflammatory response and potentially preventing autoimmunity." (PMID 25452754, 2014). "TLR9 activation also promotes the production of IgG2a and IgG2b autoantibodies recognizing host DNA, which further develop autoimmunity pathology." (PMID 22948541, 2013). "Some studies have shown that TLR9 is capable of driving autoimmunity under different conditions; for example, in mice where TLR9 was deleted from the radio-resistant compartment, such as CNS, mice developed EAE delayed kinetics and severity." (PMID 24174969, 2013). "pDCs respond to self-DNA if coupled with an antimicrobial peptide, suggesting that modified self-DNA drives autoimmunity in psoriasis by activating TLR9." (PMID 19710928, 2009). "Endosomal toll-like receptors (TLRs), such as TLR7 and TLR9, are key mediators of autoimmunity." (PMID 42112403, 2026). "Given TLR9’s significant involvement in the activation of the immune system and the development of autoimmunity, genetic variations within the TLR9 gene may have a substantial impact on an individual’s susceptibility to SLE." (PMID 40821978, 2025). "This may be partially attributed to the apparent dual role of TLR9 in both immune tolerance and autoimmunity; while TLR9 facilitates the clearance of autoreactive cells in the periphery, it is also required for their activation." (PMID 41516251, 2025). "The double-stranded DNA in the AZD1222 adenovirus vector vaccine is believed to activate Toll-like receptor 9, leading to elevated levels of type I interferons that could potentially induce pemphigus-related autoimmunity." (PMID 39203983, 2024). "CD40−/− dendritic cells were generated; these cells were pulsed with MPO and stimulated with the TLR9 ligand and their ability to induce nephritogenic autoimmunity when transferred to naïve wild type mice was compared to TLR9 stimulated MPO pulsed WT dendritic cells." (PMID 36674855, 2023). "The role of TLR9 in the induction and progression of autoimmunity is well appreciated." (PMID 36674855, 2023). "CD40 upregulation by TLR9 was critical for the induction of nephritogenic autoimmunity." (PMID 36674855, 2023). "Defining the molecular mechanisms of TLR9-induced anti-MPO autoimmunity and glomerular injury may identify critical therapeutic targets for patients with AAV." (PMID 36674855, 2023). "To confirm the increased MPO autoimmunity and resultant kidney injury was TLR9 specific and reproducible, we utilized mice deficient in TLR9 (Tlr9−/−) to generate Tlr9−/− dendritic cells and compare to TLR9 stimulated MPO pulsed TLR9 intact C57BL/6 WT dendritic cells." (PMID 36674855, 2023). "This suggests that previously intact TLR7 and TLR9 signaling may have contributed to the development of autoimmunity." (PMID 37626865, 2023). "Our study provides molecular insights into lumican and CpG-DNA interactions that may lead to molecular targets for modulating TLR9-mediated inflammation and autoimmunity." (PMID 37834438, 2023). "Having demonstrated enhanced anti-MPO autoimmunity after transfer of TLR9 stimulated MPO pulsed dendritic cells, we hypothesized that the enhanced immune responses would facilitate glomerular inflammation and injury." (PMID 36674855, 2023). "Finally, in contrast to studies of healthy individuals, loss of TLR9 mediated cytokine production in SLE patients and patients identified as “at risk” for autoimmunity has been previously reported." (PMID 35833144, 2022). "Besides, antagonism between TLR7 and TLR9 in B cell was well demonstrated in both in vivo and in vitro studies, in which TLR9 plays protective roles against autoimmunity through inhibiting TLR7-mediated autoantibody production." (PMID 35345674, 2022).